RNU5E-6P (RNA, U5E small nuclear 6, pseudogene)
Gene: Small nuclear RNA gene on chromosome 1 (44,819,883 to 44,819,997, reverse strand). Ensembl gene ENSG00000202444.
Homologues: Orthologues: chimpanzee U5 (90% identical), macaque U5 (87% identical), pig U5 (86% identical), dog U5 (84% identical), macaque U5 (84% identical). Paralogues in human: RNU5E-4P (82% identical), RNU5E-10P (81% identical), RNU5E-8P (79% identical), RNU5B-4P (77% identical), RNU5E-7P (75% identical), RNU5E-9P (74% identical), RNU5E-5P (73% identical), RNU5A-3P (72% identical), RNU5A-6P (71% identical), RNU5F-3P (71% identical), RNU5F-4P (71% identical), RNU5F-7P (71% identical), and 13 more.